CD47 (CD47 molecule)
Diseases named in the same sentence as CD47 in open-access papers (continued):
Sharing a sentence is not in itself a finding about the gene and the disease.
lymphoma (continued). "This design was supported by studies that identified synergy when CD47 and PD-L1 antibodies were combined, and others that combined CD47 mAbs with antibodies targeting tumor-specific markers such as CD20 in lymphoma models." (PMID 37958404, 2023). "Phagocytosis checkpoint blockade therapies have thus far resulted in promising human trial data, such as CD47 blocking therapeutics Magrolimab in NHL and AML, or TTI-622 in lymphoma." (PMID 33790906, 2021). "In this study, we constructed anti-CD47/CD20 bispecific antibody, showing the best efficacy of anti-lymphoma compared to the group treated with only Rituximab or only HuNb1-IgG4." (PMID 31931812, 2020). "Additionally, monoclonal antibodies targeting CD44, CD47, and CD123 have shown efficacy against lymphoma in xenograft models." (PMID 41469420, 2025). "Conversely, no statistical differences in CD47 expression were found among lymphoma subtypes, between acute and chronic leukemias and among MCT based on grading according to Patnaik/Kiupel system, nor based on lymph node metastatic status." (PMID 39535393, 2024). "Several CD47-targeted bsABs are currently being tested in early-phase clinical trials, including HX009, PD-1 × CD47 bsAB, tested in patients with relapsed or refractory lymphoma (NCT05189093)." (PMID 36900399, 2023). "While LILRB2-IgGσ was not effective, LILRB1-IgGσ significantly enhanced ADCP of lymphoma cell lines when combined with both rituximab and CD47-IgGσ." (PMID 36389667, 2022). "LILRB1 blockade complemented CD47 inhibition and thus a dual checkpoint blockade of CD47-SIRPα and LILRB1-HLA class I interactions may have the potential to improve antibody therapy of lymphomas further by enhancing ADCP by macrophages." (PMID 36389667, 2022). "Importantly, complementing rituximab and CD47-IgGσ, LILRB1-IgGσ increased ADCP of chronic lymphocytic leukemia (CLL) or lymphoma cells isolated from patients." (PMID 36389667, 2022). "However, a humanized monoclonal CD47 antibody, HU5F9-G4, is in phase 1 clinical trials for therapeutic use in advanced solid tumors and lymphomas." (PMID 35295998, 2022). "Several clinical studies have investigated the safety and efficacy of CD47 blockades, either alone or in combination with existing therapy in hematological malignancies, including myelodysplastic syndrome (MDS), acute myeloid leukemia (AML), and lymphoma." (PMID 35978372, 2022). "Lin and colleagues demonstrated that CD47 blockade ex vivo with TTI-621 (a fusion protein of an engineered SIRPα protein and human IgG1-Fc) on lymphoma cells triggered their phagocytosis by a broad subset of macrophages, including both the M1 and the M2 subtype." (PMID 34729396, 2021). "In order to further improve HuNb1-IgG4 safety and efficacy, we also established anti-CD47/CD20 bispecific antibody (BsAb) consisted of HuNb1 and Rituximab, showing more preference binding to tumor cells and more potent anti-lymphoma activity compared to HuNb1-IgG4." (PMID 31931812, 2020). "Unexpectedly, CD47 knockout also did not enhance phagocytosis of lymphoma cells, but it eliminated the pro-phagocytic effect of CD47 blockade, suggesting that the pro-phagocytic effects of CD47 blockade are due in part to Fc receptor engagement." (PMID 31205227, 2020). "Also, we established anti-CD47/CD20 bispecific antibody (BsAb) consisted of HuNb1 and Rituximab, showing more preference binding to tumor cells and more potent anti-lymphoma activity compared to HuNb1-IgG4." (PMID 31931812, 2020). "For example, the in vivo combination of anti-CD47 treatment with cyclophosphamide or paclitaxel for mouse A20 lymphoma tumors resulted in maximum synergy with chemotherapy given 1 day prior to CD47 blockade rather than 3 days after." (PMID 35582455, 2020). "Furthermore, therapeutic knockdown of CD47 in PEL cell lines and anti-CD47 antibodies promoted the phagocytosis of the lymphoma cells in vitro." (PMID 32677994, 2020).
lymphoma (continued). "Surprisingly, elimination of CD47 did not enhance the phagocytosis of lymphoma cells, although phagocytosis of these cells was still enhanced by other opsonizing antibodies as well as by restoration of CD47 expression." (PMID 31205227, 2020). "It has been shown that the use of anti CD47 antibodies lead to increased phagocytic activity of SIRP-alpha (SIRP-α) bearing macrophages, thereby indicating that overexpression of CD47 and SIRP-alpha is a lymphoma cell mechanism to evade macrophage-mediated destruction." (PMID 30101129, 2018). "Indeed, in ALK-positive lymphoma sensitive cell lines (K299, SUP-M2), previous 20 h exposure to crizotinib or lorlatinib (i.e., 0.5 μM and 0.1 μM, respectively) induced increased phagocytosis with anti-CD47 mAb." (PMID 39767726, 2024). "Interestingly, the expression of a chimeric protein composed of the cytoplasmic tail of CD47 and the extracellular domain of EGFR in T lymphoma cells lacking endogenous CD47 significantly increases their RhoA activity." (PMID 39039207, 2024). "Thus, dual checkpoint blockade of CD47 and LILRB1 may be promising to improve antibody therapy of CLL and lymphomas through enhancing ADCP by macrophages." (PMID 36389667, 2022). "Unlike CD24, mRNA expression levels of CD47 were similarly high in all lymphomas." (PMID 35625912, 2022). "Thus, the CD47:SIRPα axis is referred to as an innate immune checkpoint and is being targeted in a number of clinical trials in various cancer types including AML, breast cancer, CLL, lymphoma and head neck skin cancer." (PMID 33552071, 2020). "Recently, a Phase 1b study involving patients with relapsed or refractory non-Hodgkin’s lymphoma showed that the anti-CD47 antibody, Hu5F9-G4, combined with rituximab, exerted promising activity in patients with aggressive and indolent lymphoma, without showing clinically significant safety events." (PMID 31277366, 2019). "LILRB1-IgGσ promoted serial engulfment of lymphoma cells and potentiated ADCP by non-polarized M0 as well as polarized M1 and M2 macrophages, but required CD47 co-blockade and the presence of the CD20 antibody." (PMID 36389667, 2022).
acute myeloid leukemia (91 papers, 2013 to 2026). Acute myeloid leukemia (AML) is a group of neoplasms arising from precursor cells committed to the myeloid cell-line differentiation. "Blockade of the phagocytosis inhibitor CD47 with the antibody magrolimab has demonstrated futility with an increased risk of death in patients with acute myeloid leukemia (AML) (phase III trial ENHANCE III - NCT05079230)." (PMID 40642066, 2025). "An association was found between CD47 overexpression and poor prognosis, including acute myeloid leukemia and non-Hodgkin’s lymphoma." (PMID 38317230, 2024). "Solid tumors (e.g., bladder and BC) and hematologic cancers (e.g., acute myeloid leukemia and non-Hodgkin’s lymphoma) overexpress CD47 causing an inhibitory effect over macrophages and other myeloid cells and high levels of CD47 correlate with poor prognosis." (PMID 29544515, 2018). "Importantly, our model showed the same indication of the dose dependent toxicity associated with the CD47 blockade as in clinical trials in patients with acute myeloid leukemia or myelodysplastic syndrome." (PMID 37868989, 2023). "Magrolimab from Gilead, as the first CD47 antibody to enter clinical trials, exhibited effective antitumor activity against hematologic malignancies (e.g., acute myeloid leukemia, AML; higher-risk myelodysplastic syndrome, MDS) and solid tumors." (PMID 41226252, 2025). "Overexpression of CD47 was first identified in acute myeloid leukemia (AML), where its upregulation is linked to adverse outcomes." (PMID 41295262, 2025). "Magrolimab, an anti-CD47 monoclonal antibody, is a promising targeted agent for pediatric acute myeloid leukemia (pAML), a patient population with a high need for novel therapeutics to improve current poor clinical outcomes." (PMID 40361435, 2025). "Magrolimab, the most advanced anti-CD47 antibody, resulted in a high response rate in hematological tumors (complete response (CR): 53% in untreated acute myeloid leukemia (AML)/myelodysplastic syndrome (MDS), 10% in relapsed/refractory AML/MDS179)." (PMID 38773064, 2024). "CD47 plays a crucial role in hematological malignancies, including acute myeloid leukemia (AML), B- and T-cell acute leukemia, and non-Hodgkin's lymphoma." (PMID 38429732, 2024). "Dihydroorotate dehydrogenase inhibitor HOSU-53 shows efficacy in acute myeloid leukemia and promotes long-term survival in mouse models when combined with anti-CD47 therapy." (PMID 38646934, 2024). "For example, Hu5F9-G4, a monoclonal antibody against CD47, has demonstrated promising results in early-phase clinical trials for the treatment of Acute Myeloid Leukemia (AML) and non-Hodgkin lymphoma." (PMID 39275127, 2024). "Concomitantly, ALX Oncology in August 2023 announced an end to its ASPEN-02 and ASPEN-05 programs, which were evaluating the efficacy of its CD47 inhibitor evorpacept in myelodysplastic syndrome and acute myeloid leukaemia." (PMID 39138571, 2024). "Anti-CD47 antibodies are currently being clinically investigated in patients with myeloid neoplasms, in particular myelodysplastic syndrome and acute myeloid leukemia." (PMID 37095207, 2023). "Lemzoparlimab is a whole-human monoclonal antibody against CD47 and is used as a single agent to treat relapsed or refractory acute myeloid leukemia (NCT04202003) and MDS in phase I/II (NCT04895410)." (PMID 37484024, 2023). "Anti-CD47 combined with azacytidine in acute myeloid leukemia achieved significant anti-tumor activities in preclinical and clinical settings." (PMID 36970051, 2022). "As a matter of fact, CD47 therapeutics including Hu5F9-G4 are moving forward rapidly in the clinic, patients with acute myeloid leukemia (AML) and solid tumors are being recruited for phase I clinical trials (NCT02678338 and NCT02216409)." (PMID 35428347, 2022). "Blocking of CD47/SIRPα with anti-CD47 monoclonal antibody resulted in phagocytosis of acute myeloid leukemia cells." (PMID 33815422, 2021).
acute myeloid leukemia (continued). "Targeting of the SIRPα/CD47 axis in the context of cancer using an anti-CD47 blocking antibody enhanced phagocytosis of acute myeloid leukemia (AML) cells." (PMID 31801627, 2019). "High expression of CD47 has been shown to correlate with poorer disease survival in many cancer types, including acute myeloid leukemia, breast carcinoma, esophageal carcinoma, and gastric cancer." (PMID 30062558, 2018). "Research has demonstrated overexpression of CD47 in nearly all types of tumors, some of which include acute myeloid leukemia, non-Hodgkin’s lymphoma, bladder cancer, and breast cancer." (PMID 28077173, 2017). "In various xenograft tumor models using NOD-scid-IL2Rgammanull (NSG) mice, use of human CD47-blocking monoclonal antibodies has demonstrated superb efficacy against human acute lymphocytic leukemia, acute myeloid leukemia, leiomyosarcoma, and solid tumors." (PMID 28077173, 2017). "Another humanized anti-CD47 monoclonal antibody, Hu5F9-G4, will be clinically tested alone for treatment of recurrent/refractory acute myeloid leukemia (trial NCT02678338) and advanced solid malignancy or lymphoma (trial NCT02216409)." (PMID 28714932, 2017). "A previous study showed that a novel human SIRPα-Fc fusion protein resulted in the preferential phagocytosis of acute myeloid leukemia with the blockade of CD47/SIRPα." (PMID 27671753, 2016). "CD47 has a higher level of expression on acute myeloid leukemia blasts and leukemia stem cells, liver cancer stem cells, as well as pancreatic stem cells, as compared with their normal counterparts." (PMID 26554307, 2015). "The CD47-SIRPα interaction between acute myeloid leukemia cells and macrophages inhibits the phagocytosis by macrophages." (PMID 26554307, 2015). "Overexpression of CD47 has been found in tumor stem cells, including acute myeloid leukemia and non-Hodgkin’s lymphoma." (PMID 25658794, 2015). "Similarly, in hematologic malignancies like diffuse large B-cell lymphoma and acute myeloid leukemia, high CD47 expression has been correlated with worse clinical outcomes and resistance to treatment." (PMID 40104289, 2025). "In contradistinction, the introduction of TIGIT inhibitors could reprogram TIGIT+ M2 macrophages to the M1 phenotype, leading to increased CD47-mediated phagocytosis and ultimately benefiting the prognosis of patients with acute myeloid leukemia (AML)." (PMID 37291608, 2023). "Overexpression of CD47 is an adverse prognostic factor and could be a therapeutic antibody target on human acute myeloid leukemia stem cells." (PMID 36139679, 2022). "In this review, we explore CD47 function in normal conditions, its role in acute myeloid leukemia progression, and possible ways to block CD47 to enhance elimination of the leukemic cells improving the therapeutic options for patients with acute myeloid leukemia." (PMID 34944878, 2021). "The elevated expression level of CD47 is an adverse prognostic factor in acute myeloid leukemia." (PMID 31540045, 2019). "Additionally, a humanized anti-CD47 antibody was tested for safety and efficacy in disease models of acute myeloid leukemia (AML) and was reported to decrease tumor burden and increase survival in an AML PDX model." (PMID 28100392, 2017). "Pathologically, CD47 is highly expressed on many kinds of hematopoietic tumors, including acute myeloid leukemia (AML), chronic myeloid leukemia(CML), acute lymphoblastic leukemia (ALL), non-Hodgkin's lymphoma (NHL), multiple myeloma (MM), and solid tumors from ovarian, breast, colon, and the like." (PMID 27863402, 2016). "Additionally, the increase in CD47 expression correlated with increased disease severity in the case of low–risk myelodysplastic syndrome (MDS) to high-risk MDS and the subsequent transition to acute myeloid leukemia (AML)." (PMID 40078999, 2025).
acute myeloid leukemia (continued). "TIGIT blockade can stimulate phagocytosis by repolarizing M2-type macrophages to M1-type macrophages, synergizing with CD47 antibodies that block the "don’t eat me" signal, inducing macrophage phagocytosis of acute myeloid leukemia (AML) cells." (PMID 40821806, 2025). "CD47 is crucially linked with hematologic malignancies, such as non-Hodgkin lymphoma (NHL), acute myeloid leukemia (AML), lymphoblastic lymphoma/acute lymphoblastic leukemia (LBL/ALL), and multiple myeloma (MM)." (PMID 38983860, 2024). "More recently, targeting CD47 by SIRPα-Fc fusion protein or monoclonal antibody combined with azacitidine showed reliable efficacy and safety in some malignant hematological tumors such as myelodysplastic syndrome, acute myeloid leukemia and chronic myelomonocytic leukemia in clinical trials." (PMID 38532108, 2024). "In addition, alternatively spliced CD47 isoforms were upregulated in therapy-resistant pediatric acute myeloid leukemia stem cells, and a selective splicing modulator rebecsinib reversed the splicing deregulation and prevented expansion of the pediatric acute myeloid leukemia stem cells." (PMID 38426113, 2024). "Several anti-CD47 mAb products are actively undergoing clinical development in various forms, excluding acute myeloid leukemia (AML)." (PMID 39040441, 2024). "Magrolimab is currently the most advanced CD47-targeted therapy in development, with ongoing clinical trials for several types of cancer, including acute myeloid leukemia (AML) and solid tumors." (PMID 38188674, 2023). "In patient-derived murine xenograft models of acute myeloid leukemia (AML), an anti-CD47 antibody completely eradicated AML and provided long-term disease-free survival." (PMID 33804869, 2021). "CD47 antibodies target a variety of indications, including hematological malignancies such as non-Hodgkin Lymphoma and acute myeloid leukemia (AML), as well as solid tumors such as colorectal cancer, ovarian, and bladder cancers." (PMID 34194437, 2021). "The vast distribution of CD47 suggested its possible implication not only in diverse physiologic functions but also in pathologic situations, such as in acute myeloid leukemia (AML)." (PMID 34944878, 2021). "Increased expression of CD47 has been observed in multiple blood and solid tumors including acute myeloid leukemia (AML), non-Hodgkin lymphoma (NHL), gastric cancer, ovarian cancer, colon cancer, hepatocellular cancer and other tumor cells." (PMID 31931812, 2020). "An increased expression of CD47 has been demonstrated in multiple solid and hematological malignancies compared with normal cells, including but not limited to breast, small-cell lung, colon, ovarian, acute myeloid leukemia (AML), and acute lymphocytic leukemia (ALL) malignancies." (PMID 33469516, 2020). "The role of CD47 in cancer-mediated evasion of phagocytosis was first described in acute myeloid leukemia (AML)." (PMID 32038992, 2019). "The expression level of CD47 is higher in acute myeloid leukemia (AML) stem cells vs their normal counterparts." (PMID 31183992, 2019). "CD47 is a surface glycoprotein with many functions, such as acting as a phagocytosis inhibitor of the expressing cell, that is increased in normal hematopoietic stem and progenitor cells mobilized into the blood and several human cancer-initiating cells, such as in acute myeloid leukemia." (PMID 30539968, 2018). "CD47 expression on leukemic stem cells (LSCs) predicted worse overall survival of patients with acute myeloid leukemia (AML) and anti-CD47 blocking monoclonal antibodies preferentially enabled phagocytosis of AML leukemic HSCs." (PMID 30539968, 2018). "Recent studies show the importance of interactions between CD47 expressed on acute myeloid leukemia (AML) cells and the inhibitory immunoreceptor, signal regulatory protein-alpha (SIRPα) on macrophages." (PMID 23320069, 2013).